STAT3 (signal transducer and activator of transcription 3)
Diseases named in the same sentence as STAT3 in open-access papers (continued):
Sharing a sentence is not in itself a finding about the gene and the disease.
tumor (continued). "Together, these findings indicate that STAT3‐mediated inflammation influences the OS tumour microenvironment at each stage of tumour development leading to the progression, metastasis and drug resistance of OS." (PMID 33382511, 2021). "Corroborating findings in experiments with conditional ablation of STAT3 (Stat3ΔIEC ApcMin/+ mice), show that STAT3 is activated during the initial stages of tumor development, but STAT3 negative regulation is needed for CRC tumor invasion." (PMID 34440220, 2021). "Even STAT3, which is activated in a plethora of cancers and controls the expression of multiple genes involved in tumor initiation, progression, and chemoresistance, has been proven to be regulated by mitochondrial ROS production." (PMID 33920160, 2021). "The STAT1 and STAT3 transcription factors have been identified as major players in tumor genesis and they are being considered promising targets for cancer therapy." (PMID 33846436, 2021). "JAK/STAT3 signaling pathways play an important role in mediated IL-6 inhibition of tumor cell proliferation, invasion, and metastasis and antitumor immunity." (PMID 34745261, 2021). "On the contrary, genetic ablation of tumor-intrinsic STAT3 promotes KRASG12D-driven lung tumorigenesis in mice." (PMID 34771644, 2021). "The JAK/STAT3 signaling pathway plays a critical role in tumor proliferation and differentiation, and it has been shown to confer chemoresistance." (PMID 34168981, 2021). "Here we show that blocking inflammatory cytokine receptor signaling via STAT3 re-sensitized treatment-refractory cancer cells and abolished tumor growth in a xenograft mouse model when applied together with chemoradiotherapy." (PMID 33530306, 2021). "Accordingly, pharmacologic targeting of STAT3 overcomes resistance to afatinib and enhances anti-tumor immunity PC9-GR tumor-bearing mice." (PMID 34944848, 2021). "Taken together, W2014-S enhanced the anti-tumor effects of gefitinib in PC-9/GR xenografts through inhibition on alternatively activated STAT3 pathway." (PMID 33391507, 2021). "STAT3 activation involves multiple signaling pathways within the tumor microenvironment, thus making the antiproliferative strategies of inhibitors targeting upstream molecules difficult." (PMID 33758275, 2021). "In summary, we demonstrate the activation of STAT3 and STAT5B in feline alimentary tumour cells, and identify the activating mutation STAT5BN642H in feline EATL type II, as frequently observed in human MEITL patients." (PMID 34680385, 2021). "For example, hyperactivation of the IL6/JAK/STAT3 pathway promotes tumor metastasis and chemoresistance via induction of EMT through the upregulation of EMT-inducing transcription factors, such as Snail, Twist-1 and ZEB1." (PMID 34944855, 2021). "Among them, the activation of the JAK/STAT3 signaling pathway plays a crucial role in mediating tumor inflammatory response and promoting MDSCs proliferation." (PMID 33986819, 2021). "A study by Lee and colleagues suggested that IL-10 inhibits the IL-6/STAT3 axis on MDSCs and weaken tumour progression." (PMID 34336101, 2021). "APN or APN receptor agonist intervention has been shown to inhibit STAT3 signaling to antagonize the role of leptin in tumor cells." (PMID 33815885, 2021). "Collectively, we observed that p-STAT3 expression in tumor stroma cells was a critical contributor to cancer pathogenesis." (PMID 33854974, 2021). "ALT, a sesquiterpene lactone, is mainly extracted from the roots of Inula helenium L, which has potential anti-inflammatory, anti-bacterial, anti-fungal, anti-tumor effects and selectively inhibits STAT3." (PMID 34650433, 2021).
tumor (continued). "IHC staining of Ki67 and p-STAT3 showed that cirsiliol significantly suppressed tumor cell proliferation in the PDX mice model." (PMID 33731185, 2021). "A significant decrease in the STAT3 expression in the tumor with the combination treatment was found compared to the αPD-L1 therapy validating that MDSCs are suppressed by Mit-A in addition to αPD-L1." (PMID 34381456, 2021). "The signal transducer and activator of transcription 3 (STAT3) is an oncogenic signaling protein expressed in a variety of tumor type cells, as well as in immune cells in the tumor environment, emerging as an important molecule for immuno-oncotherapy." (PMID 33525658, 2021). "We next investigated the antitumour effect of Anwulignan on NSCLC tumour growth and the results indicated that Anwulignan significantly suppressed tumour growth by reducing the level of phosphorylated STAT3." (PMID 33523587, 2021). "Resveratrol (3,5,4′-trihydroxystilbene), a widely studied polyphenolic compound found in red grapes and several other plants, was originally reported to inhibit constitutive and IL-6-induced STAT3 activity in multiple tumor cell types." (PMID 34208282, 2021). "STAT3 is an oncogene that participates in most of the tumor development phases as a transcription factor." (PMID 33805840, 2021). "Hypoxia causes an increase in CD45 tyrosine phosphatase activity of monocytes and MDSCs, which results in the selective decrease of STAT3 activity in the hypoxic region of the tumor." (PMID 34557407, 2021). "The impact of STAT3 on lymphomagenesis in Eμ-myc mice was evaluated by comparison of tumor development in STAT3wt/wt;Eμ-myc, STAT3fl/fl;tdT;Eμ-myc, and STAT3fl/fl;tdT;CD19Cre;Eμ-myc mice." (PMID 33651821, 2021). "While combining STAT3 downregulation and anti-PD-1 decreased the manifestation of Tim-3 on Treg cells during the anti-tumor response." (PMID 33936081, 2021). "In vivo, the GBM tumor size was inversely correlated with miR-671-5p expression, but tumorigenesis was promoted by STAT3 and TRAF2 activation in the miR-671-5p-positive GBM population." (PMID 35052701, 2021). "Specifically, STAT3 is activated in 78.88% of tumour cells from all EATL I samples examined, in 87.32% of EATL II samples, and in 78.93% of PCTL cases." (PMID 34680385, 2021). "Previous studies confirmed that AKR1C1 promotes tumor metastasis via phosphorylating STAT3 and its upstream kinase JAK2 (JAK2/STAT3 pathway)." (PMID 34938341, 2021). "In PCs, IL-6 can be expressed by stromal and tumor cells, influencing the DC differentiation and function, which are inhibited by STAT3 activation." (PMID 34830209, 2021). "Curcumin enhances anti-tumor T-cell responses by inhibiting STAT3-activated inflammatory signaling in TME and also in DCs, which reestablishes the anti-tumor response again." (PMID 34485117, 2021). "In pre-clinical models of NSCLC, ruxolitinib decreases STAT3 activation, restores sensitivity to cisplatin chemotherapy, enhances apoptosis, and suppresses tumor growth." (PMID 34944848, 2021). "TAMs induce IL-10 to promote tumor growth, and secrete VEGF to promote tumor angiogenesis, via the STAT3 pathway." (PMID 34445193, 2021). "To date, the tumor-promoting roles of STAT3 signaling in NSCLC that have been well characterized include promoting angiogenesis, cell survival, cancer cell stemness, drug resistance, and evasion of anti-tumor immunity." (PMID 34944848, 2021). "Constitutive activation of STAT3 is a common feature in LC, and has also been proposed to play an important role in tumor resistance to conventional and targeted small-molecule therapies." (PMID 34490234, 2021). "STAT5B also shows high expression levels in all cases of the three tumour types, and a similar trend in the ratio of nuclear versus cytoplasmic localisation as seen for STAT3, again suggesting strong activation of STAT5B." (PMID 34680385, 2021).
tumor (continued). "Further research is needed to determine the miR‐340‐5p/STAT3 signalling potentially involved with decreased OS tumour growth in vivo." (PMID 33382511, 2021). "The upregulation of STAT3 enhances growth and invasion of tumor cells and mediates their therapy resistance." (PMID 34769099, 2021). "In summary, bufalin suppresses tumour microenvironment-mediated angiogenesis by inhibiting the STAT3 signalling pathway." (PMID 34496870, 2021). "In particular, intraperitoneal injection of garcinol in these mice resulted in inhibition of STAT3 and a reduction in tumor growth." (PMID 34440160, 2021). "Here, we report how tumor-NLRP3 activity promotes IL-6/STAT3 signaling in the bone marrow, which then regulates immunosuppressive gene expression in PMN-MDSCs resulting in a defunct cell population." (PMID 34531850, 2021). "STAT3 acts astranscriptional regulator of a variety of tumor-promoting genes such asVEGF, c-MYC, CCND1 (cyclinD1), BIRC5 (survivin), which are involved in tumor development andprogression." (PMID 33749701, 2021). "Confocal images of immunofluorescence (IF) staining indicated that the internalized PS-acet.-STAT3 peptide colocalized with STAT3 protein in the human tumor cell line." (PMID 33491667, 2021). "Our study collectively suggested that STAT3/CDK2/4/6 are important onco-immune signatures that contribute to tumor immune invasion, poor prognoses, and immune therapy failure." (PMID 33668805, 2021). "AMPK/STAT3 signaling pathway is involved in regulating tumor cell proliferation, apoptosis, and cell cycle." (PMID 34179090, 2021). "Eventually, active STAT3 stimulated a strong inflammatory response and activated the invasion/metastasis process of tumor cells." (PMID 34771727, 2021). "Autocrine IL-6 further enhanced IL-10 and IL-21 production by CD4+T cells via STAT3, supporting tumor growth and metastasis." (PMID 34917098, 2021). "This was mediated by tumor-derived G-CSF driven proliferation of myeloid-derived suppressor cells in the tumor microenvironment via STAT3, which suppressed CD8+ T cell responses against the tumor." (PMID 34604264, 2021). "Tumor-associated cells are a potent source of immunomodulating molecules, i.a., pro-inflammatory cytokine IL-1, IL-6, TNF that are involved in the stimulation of key tumor-promoting factors as STAT3 and NF-κB." (PMID 34203461, 2021). "In non‐small cell lung cancer, mesenchymal stem cells were shown to promote the formation of cancer stem cells through the IL6/JAK2/STAT3 pathway and to promote tumor invasion and migration." (PMID 33788424, 2021). "The molecular mechanism behind this observation was the activation of MAPK and STAT3 signaling pathways in tumor cells induced by CAF-secreted TGF-β1." (PMID 33946033, 2021). "Activation of the NF-κB and STAT3 inflammatory pathways was also evident (F6C), with activation of these two pathways in the non-tumour liver tissues of HCC patients previously reported to be associated with higher tumour recurrence." (PMID 34408183, 2021). "Our findings are of clinical relevance because of the crucial role of STAT3 in the control of core cancer pathways, including tumor cell proliferation, survival and tumor-promoting inflammation." (PMID 33668642, 2021). "STAT3 signalling between tumour cells, immune cells and the tumour microenvironment is mediated by factors, including IL‐6, IL‐10 and VEGF." (PMID 33382511, 2021). "To extend these in vitro findings to in vivo tumour growth, we evaluated the combination of STAT3 and CQ inhibition after injection of D283-Med-Luc cells into the cerebellum of NSG mice." (PMID 34302498, 2021). "Targeting STAT3 in tumor-bearing mice leads to tumor reduction, better survival, and a significantly higher number of activated NK cells following treatment, as compared to control mice." (PMID 34025641, 2021).
tumor (continued). "It was indicated that genetically modifying STAT3 at Lys685 decreased tumor growth due to demethylation and reactivation of several tumor-suppressor genes." (PMID 34488773, 2021). "It has been suggested that tumor-associated neutrophils (TANs) produce IL-17a, promoting EMT of gastric cancer cells through JAK2/STAT3 signaling in vivo." (PMID 34576042, 2021). "This implies that the therapies based on STAT3 modulators should be performed considering the pleiotropic functions of this transcription factor and tailored to the specific tumor type." (PMID 33435349, 2021). "This is particularly relevant for STAT3 and STAT5 which are highly expressed in Tumor-Associated Macrophages (TAMs), a critical cellular component of TIM." (PMID 33718197, 2021). "In our study, we proved that circUBE2Q2 is upregulated in GC tissues and cell lines, sponges miR-370-3p to activate the STAT3 pathway, and promotes tumor metastasis through exosomal communication, eventually promoting the malignant progression of GC." (PMID 34611143, 2021). "IL-22 binds to the IL-10R2 and IL-22R1 receptor complexes, activating the transcription factor STAT3, thereby promoting tumor progression." (PMID 34300224, 2021). "We further investigated the mechanisms of radiation resistance by measuring the expression levels of certain proteins involved in tumor proliferation- and metastasis-related pathways (IL-6/STAT3, SDF-1/CXCR4, and PI3K/AKT/mTOR)." (PMID 34539883, 2021). "Next, we examined the impacts of BL on the level of STAT3, as STAT3 signaling also participates in mediating proliferation and the survival of tumor cells." (PMID 34684488, 2021). "In vitro pharmacological inhibition of KMO reduces tumor cell viability and STAT3 and pSTAT3 expression, confirming an oncogenic role of KMO outside of its catabolic activity." (PMID 34440798, 2021). "Constitutive activation of STAT3 in OS appears to upregulate the expression of target oncogenes, leading to OS cell transformation, proliferation, tumour formation, invasion, metastasis, immune evasion and drug resistance." (PMID 33382511, 2021). "The collective findings indicated that N4 can potently inhibit PANC-1 tumor growth and induced apoptosis in vivo, and also abrogate STAT3 phosphorylation and downstream gene expression." (PMID 33420372, 2021). "The GSEA analysis has showed that NF-κB signaling, Jak-Stat3 signaling, and epithelial-mesenchymal transitions (EMT) are correlated with the high-risk score group, which are critical mediators of tumor invasion and immune evasion." (PMID 34880206, 2021). "STAT3 signalling is involved with crosstalk between tumour cells, immune cells and the microenvironment, promoting tumour‐induced immunosuppression." (PMID 33382511, 2021). "Cells from the tumour microenvironment, such as TEMSCs and TAMs, are potential therapeutic targets for OS therapy involving STAT3 signalling pathways." (PMID 33382511, 2021). "Despite its crucial role in the physiological processes, STAT3 also promotes tumor development and progression." (PMID 34375503, 2021). "Constitutive STAT3 activity in tumours increases the production of pleiotropic factors, such as IL‐10 and VEGF, which inhibit DC maturation via STAT3 signalling." (PMID 33382511, 2021). "STAT3 can be activated in tumor cells and tumor-infiltrating immune cells to further regulate the expression of oncogenes to trigger tumor progression and promote the inhibition of immune mediators." (PMID 34326876, 2021). "For instance, some studies have shown that both IL6 and OSM are capable of inducing tumour-promoting effects through STAT3, while IL6, IL11, LIF and OSM can all promote invasion and metastasis through the JAK/STAT3 and PI3K/AKT pathways." (PMID 34834425, 2021).
tumor (continued). "Evidence has demonstrated that the JAK/STAT3 pathway mediates tumor angiogenesis by increasing expression and activation of environmental hypoxia in the TME." (PMID 33936081, 2021). "STAT3 seems to have a double-sided effect on tumor progression and it is possible that it functions as an oncoprotein or a tumor suppressor protein." (PMID 33725976, 2021). "The activation of STAT3 signaling in CSCs is key to tumor progression because it promotes immunosuppressive factors and angiogenesis." (PMID 34179009, 2021). "Similar results were shown in mouse and patient-derived xenografts with increased expression of IL-6 in combination with PTEN loss, which results in constitutively active AKT, enhanced expression of STAT3, and promoted tumor progression." (PMID 34638338, 2021). "STAT3 modulation should be tailored according to the specific tumor type, in order to avoid promoting cancer invasion." (PMID 34440220, 2021). "This study uncovers that the inflammatory signaling hub STAT3 conspires with the cell fate regulator NOTCH in rendering tumor cells refractory to chemoradiotherapy." (PMID 33530306, 2021). "We generated Eμ-myc mice that either lacked the IL-6 gene, or lacked the STAT3 gene specifically in B cells to determine the role of the IL-6/JAK/STAT3 pathway in tumor development." (PMID 33651821, 2021). "Conversely, depletion or attenuation of STAT3 signaling in myeloid populations promoted anti-tumor immune responses in the form of CD8+ T cells and suppressed tumor development." (PMID 33917037, 2021). "In CRC, HSP110 promotes the proliferation of tumor cells by activating signal transducer and activator of transcription 3, STAT3." (PMID 35047001, 2021). "Tumor-bearing mice receiving OLT1177 exhibited significantly less constitutive STAT3 (p<0.05) and pSTAT3(Y705) (p<0.05) in the bone marrow compared to vehicle-treated mice." (PMID 34531850, 2021). "Activated STAT3 can regulate the expression of various genes involved in cancer pathogenesis, including angiogenesis, tumor migration, and cell survival." (PMID 34638708, 2021). "Recent research has shown that the JAK2/STAT3 pathway plays a key role in tumorigenesis and progression of a variety of tumor types." (PMID 33788424, 2021). "NSCLS cell lines A549 and PC-9 with high level of phosphorylated STAT3 were treated with W2014-S and W2014-R to determine the anti-tumor effect in cell model." (PMID 33391507, 2021). "More importantly, aberrant STAT3 activation plays a key role in tumor progression, in the development of resistance to therapy, and relapses." (PMID 34885171, 2021). "We treated HCT116 tumor cells with either napabucasin or PS-acet.-STAT3 peptide, followed by Western blotting to assess phosphorylated STAT3 (p-STAT3) and p-STAT5 levels." (PMID 33491667, 2021). "The tumor mitotic index (Ki-67) and STAT3 signaling in tumor tissues were evaluated by immunohistochemistry (IHC) and western blotting." (PMID 33391507, 2021). "ETBF can rapidly activate the STAT3 signaling pathway and promote Th17 cells to secrete IL-17; thus, IL-17-dependent NF-κB and Wnt pathways are activated to establish inflammatory tumor microenvironment in the gut." (PMID 33959032, 2021). "Garcinia livingstonei T. Anderson (GLT) elevates the expression level of iNOS and IL-12, and reduces the expression levels of IL-6, TNF-α, Arg-1, and IL-1β on TAMs to impede the tumor progression through the inhibition of STAT3, JNK, and ERK signaling pathway." (PMID 33748122, 2021). "A significantly lower level of phosphorylated STAT3 (p-STAT3) was recently detected in tumor-derived MDSCs than in peripheral MDSCs." (PMID 33816301, 2021). "The CAFs‐released cytokines identified in the present study can eventually stimulate the activation of several signaling pathways, especially Stat3 and NF‐κB, in tumor cells." (PMID 34459125, 2021).